ATG12P2 (autophagy related 12 pseudogene 2)
Gene: Processed pseudogene on chromosome 2 (222,904,640 to 222,905,055, reverse strand). Ensembl gene ENSG00000224121.
Diseases named in the same sentence as ATG12P2 in open-access papers:
ATG12P2 is named in the same sentence as 1 disease in open-access papers, as found by Europe PMC text mining. Sharing a sentence is not in itself a finding about the gene and the disease.
ATG12P2 shares sentences with these, for which no sentence is quoted: breast tumors (1 paper).